TACC1 (transforming acidic coiled-coil containing protein 1)
Diseases named in the same sentence as TACC1 in open-access papers (continued):
Sharing a sentence is not in itself a finding about the gene and the disease.
cancer (24 papers, 2002 to 2025). A tumor composed of atypical neoplastic, often pleomorphic cells that invade other tissues. "Among the three hypomethylated loci with delta beta =< 0.1, one was the TACC1 gene, which is known to be associated with other cancers." (PMID 36430738, 2022). "Alternative splicing (AS) of TACC1 produces multiple variants, which are of great significance in cancer biology." (PMID 34897285, 2021). "Interestingly, TACC1 association with the RUNX family occurred in cancer of the myeloid line." (PMID 37371794, 2023). "Moreover, ChIP-chip assays yielded a total of 48 genes enriched in at least three of the seven primary samples including genes associated with cell cycle such as ARGHEF2, CCNA2, CDKN2D, GAK2, ORCL6, PCPNP, and TACC1 and genes associated with cancer such as AR, AXIN2, IKBKG, ETS1, PTPN11, and WNT2B." (PMID 23300998, 2013). "Igfbp5, Enpp2, Ctsh, Lpl, and Tacc1 are the top five genes correlated with the E2 branch in pseudotime and all are currently under investigation as cancer biomarkers." (PMID 30418965, 2018). "TACC1 mRNA expression was stronger in pT2 and pT3 carcinomas than in benign prostate tissue samples." (PMID 17137506, 2006). "A similar dichotomy in the expression pattern of TACC1 has been observed, in that TACC1 can be upregulated or lost in cancer." (PMID 15918899, 2005). "TACC1 plays a role in tumor growth by binding to many different complexes, and the downregulation of human TACC1 may alter how polarized cells control mRNA homeostasis and contribute to the development of cancer." (PMID 37907864, 2023). "It was reported that in mouse cancer, full-length TACC1 promotes the phosphorylation of AKT." (PMID 34897285, 2021). "Many studies reported that TACC1 expression was modified in several cancers." (PMID 32850962, 2020). "We propose that alteration in the pattern of TACC1 mRNA splicing in cancer cells might lead to perturbation of TACC1 function." (PMID 12087473, 2002). "Changes in TACC1 mRNA splicing patterns in cancer cells may interfere with TACC1 function." (PMID 34897285, 2021). "This suggests that TACC1 overexpression caused by FGFR1-TACC1 fusion could participate in neoplastic transformation through deciliation caused by increased Aurora A activity and deregulated cell division, similar to FGFR3-TACC3 cancers." (PMID 34207779, 2021). "TACC1 gene belongs to the TACC gene family that encodes centrosomal proteins that may play roles in microtubule regulation and spindle function, and, thus, may be an important driver of genomic instability in cancer cells." (PMID 32850962, 2020). "Furthermore, TACC1 mRNA expression was strong in HR stage carcinoma samples." (PMID 17137506, 2006). "FGFR1, TACC1 and WT1 were overexpressed in HR LuCaP 23.1 carcinoma cells." (PMID 17137506, 2006). "In addition, serological responses to seven antigens (including TACC1, NUCB2, Tbdn-1 and granulin etc.)were restricted to cancer patients and investigation of their relevance for sero-diagnosis or prognosis is in progress." (PMID 12087473, 2002). "The three human TACC proteins, TACC1, TACC2, and TACC3, are core components of the centrosome and have non-overlapping functions in the normal cell and the cancer cell." (PMID 21113414, 2010).
tumor (15 papers, 2002 to 2023). "In addition, our data provide the evidence that TACC1 over-expression is associated with venous invasion, implying its possible role in tumor metastasis." (PMID 24358147, 2013). "Therefore mutations in the structure and function of TACC1 in tumours could mislocalize the protein in a cell subcompartment or deplete one of them." (PMID 20078863, 2010). "The 2.278-fold increase in HR of tumor-related death in TACC1 group was also obviously significant (P<0.001; 95% CI 1.803–5.959)." (PMID 24358147, 2013). "Further studies will be focused on exploration of the possible functional differences between TACC1 isoforms, definition of cell populations that express Tbdn-1 acetyltransferase and investigation of its possible role in tumour angiogenesis." (PMID 12087473, 2002). "Further, it was disclosed that miR-22-3p exerts its tumor-suppressive function through targeting transforming acidic coiled-coil containing protein 1 (TACC1), which reinforces anchorage-independent growth and protects cells from apoptosis via elevating the level of PI3K." (PMID 33435156, 2021). "In addition, 11 tumor-specific exonic variants were identified in six genes spanning the 8p11-p12 genomic region (RAB11FIP1, GPR124, ADAM2, LSM1, TACC1, ZNF703)." (PMID 29844878, 2018). "Whether the combined expression of NPM, TFF3 and TACC1 contributes a growth advantage of tumour must be further determined by in vitro and clinical studies." (PMID 24358147, 2013). "In conclusion, TFF3 and TACC1 over-expression in tumor epithelial cells of surgically resected gastic adenocarcinoma could independently predict a shorter survival." (PMID 24358147, 2013). "This function of TACC1 might account for its involvement in several forms of tumour development." (PMID 20078863, 2010). "TACC1 has been also reported to stimulate the RAS and PI3K pathways playing an oncogenic role in tumor formation in the murine mammary gland." (PMID 32850962, 2020). "In the five iCCA patients with FGFR2 fusions (BICC1 (n=2), KIAA1217, TACC1, CCDC6), two confirmed PRs and a SD (25% tumour reduction) of 24–41 weeks duration were observed." (PMID 28972963, 2017). "Notably, TIPARP was highly expressed in the tumor relative to the normal group expression, and CD24, TACC1, HSD17B10, and CAV1 were less expressed in the tumor relative to the normal group." (PMID 37907864, 2023). "TACC1 was expressed in the cytoplasm of tumor epithelial cells (positive 49% vs. 51% negative) (Figure." (PMID 24358147, 2013).
CNS tumor (1 paper, 2025). "The identification of the FGFR1: TACC1 fusion and methylation profiling was pivotal in achieving an accurate diagnosis, highlighting the critical role of molecular evaluation as a complement to histopathology in CNS tumor diagnostics." (PMID 40677455, 2025).
infection (1 paper, 2018). The state of being infected such as from the introduction of a foreign agent such as serum, vaccine, antigenic substance or organism. "To gain further insights into the immune responses that could explain the susceptibility of TACC1 mice, we made use of the more physiological low dose infection model applying 100 CFU Mtb via the aerosol route." (PMID 29675017, 2018). "Analysis of the immune response during infection revealed that T cells from TACC1 mice exhibited reduced frequencies of IFN-γ+ CD4 T cells indicating the importance of T cell-intrinsic FAS for mounting Th1 responses." (PMID 29675017, 2018). "Indeed, when infected with a high aerosol dose of Mtb, TACC1 mice succumb to infection as early as 4 weeks, highlighting the importance of de novo FAS for IFN-γ production by Th1 and CD8+ T cells." (PMID 29675017, 2018).
TACC1 also shares sentences with these, for which no sentence is quoted: glioma (8 papers); glioblastoma (6); extraventricular neurocytoma (4); cervical cancer (2); dysembryoplastic neuroepithelial tumor (2); adenocarcinoma (1); astrocytomas (1); bladder carcinomas (1); brain cancer (1); colorectal cancer (1); familial melanoma (1); ganglioglioma (1); human papillomavirus infection (1); Insulin resistance (1); lung squamous cell carcinoma (1); multiple myeloma (1); neuroendocrine tumor (1); neuroepithelial tumor (1); pediatric cancer (1); pilocytic astrocytoma (1); rhabdomyosarcoma (1); serous papillary carcinoma (1); spindle cell tumors (1); type 2 diabetes mellitus (1).